RETN (resistin)
Diseases named in the same sentence as RETN in open-access papers (continued):
Sharing a sentence is not in itself a finding about the gene and the disease.
Sepsis (continued). "We identified and validated CD27, KLRB1, RETN, and CD163 as key biomarkers of sepsis by integrating transcriptome and single-cell data using bioinformatics and machine learning." (PMID 41472734, 2025). "In conclusion, our research revealed that CD27, KLRB1, RETN, and CD163 are highly specific and sensitive biomarkers for sepsis." (PMID 41472734, 2025). "For example, the outgoing signaling of C1_CD36, C3_B, C9_STOM, and C10_ULK1 cells was dominated by “pattern 1,” which included RESISTIN and VISFATIN in sepsis." (PMID 37919720, 2023). "Several studies indicate that resistin and NGAL are increased in sepsis patients and serve as markers for disease severity." (PMID 37342494, 2023). "Moreover, we found that CD3, CD247, CD2, and CD40LG were negatively correlated with KC, whereas MMP-9, LCN2, and RETN were positively correlated with KC, suggesting that these candidate hub genes may regulate geriatric sepsis-induced ARDS by modulating the recruitment of neutrophils to the lung." (PMID 37822934, 2023). "Our findings showed that the expression of RETN, S100A12, IL18R1, and KL was higher in the sepsis group, while the expression of GZMB, HLA-DPA1, CD3E, IL2RB, CD3G, and CCR3 was higher in the control group." (PMID 38124071, 2023). "As shown in these figures, the expression levels of RETN, S100A12, IL18R1, and KL were higher in the sepsis group, while that of GZMB, HLA-DPA1, CD3E, IL2RB, CD3G, and CCR3 were higher in the normal group (p < 0.05)." (PMID 38124071, 2023). "In conclusion, the present study identified core immune‐related DEGs between severe burns and sepsis, including IL10, RETN, THBS1, FGF13, LCN2 and MMP9." (PMID 37060578, 2023). "Therefore, resistin could be a potential drug candidate for sepsis treatment." (PMID 37834432, 2023). "Drawing upon the insights gleaned from our murine sepsis-induced ARDS model and human subjects afflicted with sepsis-induced ARDS, we selected CD247, CD2, CD40LG, KLRB1, LCN2, and RETN as the foci of our subsequent investigation." (PMID 37822934, 2023). "In sepsis, monocytes were negatively correlated with CD247, CD2, and CD40LG, while positively correlated with LCN2 and RETN." (PMID 37822934, 2023). "Concerning the transcripts related to “neutrophil activation,” matrix metalloproteinase 8 (MMP8) showed the highest upregulation in sepsis samples, followed by olfactomedin 4 (OLFM4) and resistin (RETN)." (PMID 36443881, 2022). "The plasma levels of resistin, ICMA-1, IL-6, IL-10 and MCP-1 of the patients with sepsis were statistically higher than those of the patients with COVID-19 at all measurement points." (PMID 35784283, 2022). "Cox regression analyses and Kaplan-Meier curves were used to assess the impact of resistin on ICU and overall survival during an almost three-year follow-up among all critical care patients and the subgroups of sepsis and non-sepsis patients." (PMID 19545363, 2009). "In contrast, serum resistin concentrations were substantially reduced in non-shock sepsis patients (P < 0.05)." (PMID 40568710, 2025). "Serum resistin concentrations in both non-shock and shock sepsis patients were noticeably increased than those in healthy individuals (P < 0.01)." (PMID 40568710, 2025). "As a ligand, RETN engages receptors such as TLR4 and CAP1 and activates the NF-κB signaling pathway, which promotes release of large amounts of proinflammatory cytokines and drives the systemic inflammatory response in early sepsis." (PMID 41472734, 2025). "And nonsurvivors with sepsis without shock demonstrated significantly elevated serum S100A8/A9 levels (P < 0.001), whereas resistin levels remained comparable between septic shock and non-shock sepsis nonsurvivors (P = 0.38)." (PMID 40568710, 2025). "Although resistin did not predict mortality in sepsis patients, it effectively differentiated sepsis patients from non-sepsis patients and healthy individuals, as reflected by its increased serum levels in sepsis." (PMID 40568710, 2025).
Sepsis (continued). "Based on this study’s findings and existing research theories, we propose that CD27, KLRB1, RETN, and CD163 may collaboratively regulate immune homeostasis in sepsis through their interactions." (PMID 41472734, 2025). "The median resistin concentration at admission was 66.93 ng/mL (6.15-278.9 ng/mL) in sepsis patients, 24.91 ng/mL (9.01-167.2 ng/mL) in non-septic ICU patients, and 7.63 ng/mL (1.93-21.68 ng/mL) in the healthy comparison group." (PMID 40568710, 2025). "On the day of admission, serum resistin concentrations in Gram-negative (G-) sepsis patients were considerably elevated relative to Gram-positive (G+) infected sepsis patients." (PMID 40568710, 2025). "The cut-off values for RETN levels in the diagnosis of sepsis have not been consistently reported across studies, even when the same assay is used, which significantly impedes the clinical application of this biomarker." (PMID 40416430, 2025). "The concentrations of S100A8/A9 and resistin in sepsis patients were noticeably increased relative to non-sepsis patients and healthy controls." (PMID 40568710, 2025). "Although resistin cannot predict the death of sepsis patients, it can still effectively distinguish sepsis patients from non-sepsis patients and healthy individuals." (PMID 40568710, 2025). "Additionally, this study demonstrated significant correlations between resistin, S100A8/A9, CRP, and IL-6 in sepsis patients." (PMID 40568710, 2025). "The clinical relevance of this objective lies in the continued lack of clarity regarding the pathophysiologic role of resistin in human sepsis, an issue which has been debated since 2007." (PMID 35286340, 2022). "The current study also provides further evidence that resistin is more likely to be a marker of acute inflammation rather than a disease-mediating cytokine in acute sepsis." (PMID 35286340, 2022). "Rko mice did not demonstrate an increase in blood resistin concentration following the onset of sepsis (P = 0.62 at 6 h and P = 1.0 at 24 h)." (PMID 35286340, 2022). "Some investigators have demonstrated higher circulating resistin concentrations in sepsis non-survivors, whereas others have been unable to confirm this relationship." (PMID 35286340, 2022). "Ex vivo resistin-induced impairment of neutrophil function do not appear to translate to increased sepsis severity or poorer outcomes in vivo following CLP." (PMID 35286340, 2022). "According to the findings of a 2009 German study by Koch, resistin serum concentrations were significantly higher in sepsis than in non-sepsis patients hospitalized in ICU." (PMID 31555623, 2019). "It was noteworthy, that in STSS patients a strong correlation between IL-8 levels and HBP (r = 0.84, p = 0.009), as well as IL-8 and resistin (r = 0.86, p = 0.006) was observed, whereas no such correlation was evident in the other sepsis cohorts." (PMID 26887258, 2016). "Remarkably, non-survivors in the subgroup of non-sepsis patients had significantly higher resistin levels than survivors." (PMID 19545363, 2009). "The subgroup analysis of septic and non-septic patients showed significantly higher resistin serum levels in the group of septic patients (median 24.2 ng/ml in patients with sepsis vs. 10.5 ng/ml in ICU patients without sepsis, P < 0.001)." (PMID 19545363, 2009). "Remarkably, in patients without sepsis, resistin was correlated with the APACHE II score on admission (r = 0.481, P = 0.005)." (PMID 19545363, 2009). "Similarly, serum resistin concentrations were also substantially raised in sepsis patients in comparison with both non-septic ICU patients and healthy controls." (PMID 40568710, 2025). "Additionally, resistin was significantly correlated with S100A8/A9, suggesting that the combination of these biomarkers could be useful for immune typing of sepsis patients." (PMID 40568710, 2025).
Sepsis (continued). "Moreover, resistin levels were noticeably increased in septic shock patients relative to those without shock, providing insight into the severity of sepsis." (PMID 40568710, 2025). "Our findings suggest that resistin may provide feasible protection for sepsis patients, particularly those with severe cases, without serious side effects." (PMID 37834432, 2023). "Moreover, resistin has been potentially introduced as a marker of proinflammatory status (cytokine-like) in relation to sepsis and in other nonseptic critical pathologies." (PMID 31881807, 2019). "However, patients with septic shock show drastically elevated plasma resistin concentrations when compared to postoperative critically ill patients without sepsis or AKI." (PMID 28779451, 2017). "Our observation that high resistin is a predictor for an unfavorable prognosis only in non-sepsis, but not in sepsis, patients further suggests that the massive acute phase response, as mirrored by elevated resistin, is of considerable harm in the absence of infection." (PMID 19545363, 2009). "Neonates with sepsis may be separated from the control group by seeing elevated levels of CRP, platelets, absolute neutrophil count, immature to total neutrophil ratio, neutrophil-to-lymphocyte ratio, and red cell distribution width, and especially higher resistin levels (all p<0.001)." (PMID 38562275, 2024). "Notably, within the PPI network analysis, key proteins including ICAM1, Resistin, TIMP1, VWF, CRP, and HMGB1 were identified at the central nodes of the network module, revealing a significant difference (P < 0.05) between the normal group and the sepsis group." (PMID 38951753, 2024). "Circulating resistin levels were increased in hospitalized COVID-19 patients and in non-COVID-19 critical patients which is in line with previous findings demonstrating increased levels in patients with sepsis and septic shock as well as critically ill patients without infection." (PMID 36509969, 2023). "Further survival analysis revealed that while the expression levels of KLRB1, RETN, and CD163 significantly influenced sepsis prognosis, CD27 did not demonstrate statistical significance." (PMID 41472734, 2025). "CD247, CD2, CD40LG, and KLRB1 displayed a positive correlation with CD8+ T cells and CD4+ T cells in both COVID-19 and sepsis cases, while LCN2 and RETN showed a negative correlation." (PMID 37822934, 2023). "Additionally, surviving patients with sepsis without shock demonstrated significantly elevated serum S100A8/A9 levels (P < 0.0001), whereas those with septic shock showed markedly increased resistin concentrations (P < 0.001)." (PMID 40568710, 2025). "In adult intensive care unit (ICU) patients, resistin was superior to CRP in distinguishing sepsis from systemic inflammatory response (SIRS) due to trauma without infection, and the level of resistin was significantly higher in sepsis compared to trauma related SIRS." (PMID 30517161, 2018). "Notably, measurement of IL-8 levels in the patients revealed a positive correlation between IL8 with HBP and resistin, respectively, in STSS patients, but not in the large sepsis cohort." (PMID 26887258, 2016).
endothelial dysfunction (54 papers, 2006 to 2025). In vascular diseases, endothelial dysfunction is a systemic pathological state of the endothelium (the inner lining of blood vessels) and can be broadly defined as an imbalance between vasodilating and vasoconstricting substances produced by (or acting on) the endothelium. "Leptin and resistin have been implicated to cause endothelial dysfunction by promoting oxidative stress." (PMID 35711339, 2022). "In T2DM women, resistin levels correlated with markers of renal function, systemic inflammation and endothelial dysfunction and were independently associated with a higher CHD risk." (PMID 34496965, 2021). "In women with CHD, the higher degree of chronic inflammation and endothelial dysfunction is likely linked to the higher resistin levels." (PMID 34496965, 2021). "Significant correlations were noted between resistin levels and all the investigated inflammatory and endothelial dysfunction markers, although the strength of the association was greater for IL-6 and sVCAM." (PMID 34496965, 2021). "A positive association of vascular inflammation with endothelial dysfunction, resistin levels, pericardial adipose tissue, and visceral fat area has also been reported." (PMID 30274193, 2018). "Some data suggest that resistin has a role in inflammatory processes, and resistin seems to directly cause endothelial dysfunction." (PMID 27746590, 2016). "Additionally, adipocytokines secreted by visceral fat, such as leptin and resistin, promote inflammation and endothelial dysfunction, leading to vasoconstriction and increasing the risk of vulnerability and rupture of atherosclerotic plaques." (PMID 40697549, 2025). "Moreover, the PSMD3 rs3087852 SNP has previously been associated with circulating levels of resistin, an adipokine secreted primarily by mononuclear cells that promotes pro-inflammatory responses and contributes to endothelial dysfunction." (PMID 41441015, 2025). "However, in this study, we mainly focused on the interaction of resistin and its genetic variant with clinical parameters of endothelial dysfunction in the studied population." (PMID 35565757, 2022). "In humans, recent studies suggest that resistin directly causes endothelial dysfunction by increasing endotelin-1 (ET-1) secretion as well as vascular cell adhesion protein 1 (VCAM1) and monocyte chemoattractant protein-1 (MCP-1) and by reducing the nitric oxide synthetase." (PMID 35011183, 2021). "Furthermore, resistin levels were associated with renal function, atherogenic lipid profile, and with inflammatory and endothelial dysfunction factors." (PMID 34496965, 2021). "In patients with diabetic foot lower plasma levels of adiponectin and higher plasma levels of IL-6 and resistin could be linked to endothelial dysfunction and progressive arterial stiffening." (PMID 28056981, 2017). "This sympathetic imbalance, coupled with resistin-induced endothelial dysfunction, fosters a microenvironment conducive to adverse cardiac remodeling and functional decline." (PMID 41347124, 2025). "Subsequently, adipose tissue secretes pro-inflammatory cytokines such as TNF-α, IL-6, and resistin, while reducing protective adipokines like adiponectin, contributing to IR, endothelial dysfunction, and systemic inflammation, a process termed metaflammation." (PMID 40959347, 2025). "Elevated resistin levels have been shown to promote endothelial dysfunction, VSMC proliferation, and oxidative stress, which contribute to the development of hypertension, atherosclerosis, and other CVDs." (PMID 39682585, 2024). "Current knowledge in this regard therefore suggests that an increase in visfatin and resistin levels contributes to the pathogenesis of endothelial dysfunction, which subsequently leads to a reduction in plasma concentrations of adiponectin." (PMID 38809909, 2024).
endothelial dysfunction (continued). "Accumulating data confirm that resistin promotes endothelial dysfunction and pro-inflammatory activation, which leads to an acceleration of the development of subclinical atherosclerosis." (PMID 37623488, 2023). "Our study aim was to estimate the putative association between serum resistin concentration, resistin SNV (−420G/C) distribution, and markers related to endothelial dysfunction, including salt taste preference in hypertensive patients." (PMID 35565757, 2022). "Adipose tissue (morphometry), plasma adiponectin, TNF-α, resistin (multiplexing) and biochemical chemistry were analyzed; as well as endothelial dysfunction (Flow Mediated Dilation, FMD) and atherogenesis (Carotid Intima Media Thickness, CIMT)." (PMID 33469087, 2021). "Emerging evidence proposed that resistin plays a pathogenic role in CVD, including inflammation, endothelial dysfunction, thrombosis, and smooth muscle activity." (PMID 34886472, 2021). "We investigated resistin concentration and its potential associations with CVD risk factors, as well as with inflammation and endothelial dysfunction markers in a group of outpatient obese post-menopausal women." (PMID 34496965, 2021). "A variety of cardiovascular effects of resistin were reported since its discovery in 2001, such as the induction of endothelial dysfunction and the promotion of ischemia-reperfusion myocardial injury." (PMID 30353146, 2018). "Increased resistin concentration can act as a mediator of endothelial dysfunction by promotion of endothelial cell activation via the release of ET-1." (PMID 29081601, 2017). "It was evidenced that resistin can have prooxidative properties and can act as prooxidant mediator for endothelial dysfunction, which in other studies was reported." (PMID 29081601, 2017). "In vascular cells, resistin enhances vascular smooth muscle cell proliferation, endothelial dysfunction, and promotes monocyte adhesion and infiltration." (PMID 24465803, 2014). "Moreover, resistin is shown to induce endothelial dysfunction in blood vessels and promotes endothelial-monocyte adhesion and infiltration." (PMID 36562851, 2023). "For example, future work would examine nitrates/nitrites or citrulline, nitric oxide synthase metabolites, adiponectin, resistin, or leptin concentrations so as to confirm the herein revealed endothelial dysfunction, especially if correlated to hormones levels." (PMID 35327688, 2022). "Recombinant resistin was found to induce endothelial dysfunction in vitro, due to increased expression of endothelin-1, vascular cell adhesion molecule-1, and enhanced vascular smooth muscle cells migration, ultimately contributing to atheromatous plaque formation." (PMID 34886472, 2021). "Therefore, resistin was found to promote microvascular inflammation, endothelial dysfunction, VSMC proliferation, and plaque formation." (PMID 33240938, 2020). "Complementary experiments to measure plasma biomarkers of inflammation, oxidative stress, and endothelial dysfunction such as resistin, ICAM-1, VCAM-1, and E-selectin could be useful to refine the mechanism of action of MOI." (PMID 31214278, 2019). "Measurements of proinflammatory cytokines and oxidative stress in obese children revealed many markers that might contribute to endothelial dysfunction such as higher levels of leptin, resistin, and IL-6 as well as lower levels of adiponectin." (PMID 26011530, 2015). "The use of antioxidants may be an effective strategy in preventing resistin-induced endothelial dysfunction." (PMID 24386395, 2013). "To investigate whether oxidative stress is involved in resistin-induced endothelial dysfunction, we analyzed the levels of O2− using DHE staining and flow cytometry analysis." (PMID 24386395, 2013). "It has been recently reported that resistin may play an important role in potentiating endothelial dysfunction through oxidative stress." (PMID 22701635, 2012).